SOX2 (SRY-box transcription factor 2)
Diseases named in the same sentence as SOX2 in open-access papers (continued):
Sharing a sentence is not in itself a finding about the gene and the disease.
cancer (continued). "Of which, the cancer stem cell markers such as SRY (sex determining region Y)-box 2 (SOX2) and Nestin have gotten researchers interested." (PMID 27150062, 2016). "PRI-2191, PRI-1907 and PRI-1917 downregulated the expression of NANOG, OCT3/4 and SOX2, i.e., pluripotent stem cell-related genes involved in the stem cell renewal, which are aberrantly overexpressed in several cancers." (PMID 27314328, 2016). "Further studies of the functional role of SOX2 in human cancers are required to clarify these differences." (PMID 27411517, 2016). "In summary, we show that the aggressive clones derived from CD49f+/CD44+/CD24− single cells activate the OCT4/SOX2/lincRNA-RoR signaling axis to maintain cancer stem cell self-renewal and regulate differentiation." (PMID 27374087, 2016). "Transcription factor SOX2 has been identified as an oncogene in many cancers and plays important roles in cancer stem cells (CSC), EMT, and metastasis of cancer cells." (PMID 27791206, 2016). "STAT3 also regulates self-renewal in cancer stem cells by systematically regulating canonical stemness genes including Nanog, Sox2, Oct4 and myc." (PMID 27472461, 2016). "Our results confirmed SOX2 is also a direct transcriptional target of the JAG1/NOTCH signaling pathway in cancer cells." (PMID 27029061, 2016). "Sox2 expression in these cancers has been shown to correlate with cancer stemness properties, such as chemoresistance, tumor initiation, and self-renewal." (PMID 27821172, 2016). "Functional experiments suggest that SOX2 is responsible for cellular proliferation, tumor invasion and migration, self-renewal, maintenance in cancer stem cell populations, and lung tumorigenesis." (PMID 27150062, 2016). "Further investigation of G-quadruplex induced regulation of such a key gene as SOX2 would be of the extreme importance for the understanding of cancer and neural development." (PMID 27551915, 2016). "Using our in vitro model, we found that SOX2 expressing cells displayed several characteristics of cancer stem cells; such as a decreased proliferative rate, a spheroid growth pattern, and increased expression of stem cell markers CD24 and CD44." (PMID 27411517, 2016). "In this type of cancer, SOX2 has been shown to increase cellular proliferation and survival, to stimulate epithelial-mesenchimal transition (EMT) and to promote castration-resistant disease." (PMID 26540632, 2016). "SOX2 is a transcription factor, thus SOX2 downstream genes that exert a tumorigenic effect have been actively sought in such different types of cancers." (PMID 26846300, 2016). "With progress of cancer biology, a number of genes have been investigated for predicting prognosis of NSCLC, such as cancer stem cell markers SRY (sex determining region Y)-box 2 (SOX2) and Nestin." (PMID 27150062, 2016). "We therefore performed Q-PCR and found that drug treatment upregulated the expression of these cancer stem cell-associated genes in all three cell lines, including ALDH1, SOX2, c-MYC, OCT4, and NANOG." (PMID 26506421, 2016). "Recent work has shown that SOX2 is not only expressed in ~20 different types of human cancer, it also appears to influence drug resistance in at least six of these cancers." (PMID 27145457, 2016). "In this regard, the SOX2 gene is amplified in several cancers, and high levels of SOX2 correlate with poor prognosis in many cancers." (PMID 27145457, 2016). "Significantly, TZD action appears to be restricted to the high Sox2 expressing cancer stem cell population and is dependent on PPARγ expression." (PMID 27528232, 2016). "In gliobastoma, Sox2 has been reported to regulate the expression of key genes involved in cancer stemness; Sox2 knockdown abolished de-differentiation and the acquisition of CSC phenotype." (PMID 26683522, 2016).
cancer (continued). "By investigating the expression level of the three crucial stem cell markers Sox2, Nanog and Oct4, we want to provide evidence for the existence of cancer stem cell-like traits in tamoxifen resistant cells, which are known to generate drug resistance." (PMID 27409163, 2016). "In a general perspective SOX2 has been found to antagonize the Hippo pathway to maintain ‘stemness’ in cancer cells." (PMID 27074562, 2016). "YY1 frequency of expression was associated with the SOX2, BMI1 and OCT4 frequency of expression across many cancers, though the type of association varied." (PMID 27225481, 2016). "Some studies have revealed that miR-126-3p inhibits cancer growth directly by targeting Sox2, p85β (PIK3R2), IRS1, VEGF and other genes." (PMID 27191494, 2016). "Growth of many cancers is dependent on mechanisms that specify developmental lineages, including SQCCs being dependent on SOX2." (PMID 27880766, 2016). "FGFR1 expression was associated with higher pN (p = 0.023), pT (p = 0.003) stages, lymphovascular invasion (p = 0.010), p-cadherin (p = 0.028), synaptophysin (p = 0.009) and SOX2 expression (p = 0.034) in luminal A cancers." (PMID 26673008, 2016). "We chose five lncRNAs (HOTAIR, HOXA-AS-2, lincRNA—ROR, MALAT1, and ANRIL) and three mRNA Homeobox A13 (HOXA13), SRY-box 2 (SOX2) and POU class 5 homeobox 1 (POU5F1/OCT4) implicated in a range of cancers, including UBC." (PMID 26800519, 2016). "Oct-4 and Sox2 are core regulators in stem cell self-renew and validated as cancer stem cell target." (PMID 27505247, 2016). "In few previous studies, the suggested role of SOX2 in cancer stem cell differentiation has, in difference to our study, at least partly been linked to EMT related factors." (PMID 27411517, 2016). "The importance of SOX2 in cancer stem cells has been highlighted recently by two independent studies." (PMID 27029061, 2016). "Sox2 is a master regulator of stem cell maintenance in embryonic stem cells, tissue specific stem cells, and cancer stem-like cells." (PMID 26444992, 2015). "The downregulation of SOX2 alone was enough to bring down the self-renewable capacity of cancer cells with stem like characteristics." (PMID 26176230, 2015). "The role of G9a in regulating Sox2 protein stability in mouse ESCs is of particular interest because cancer cells share common characteristics with ESCs, i.e., cancer stem cells have the capacity for self-renewal." (PMID 26492085, 2015). "Stem cell-specific transcription factors, such as Nanog, Sox2 and Oct4 alone and in combination have been studied in embryonic stem (ES) cell pluripotency and cancer stem cell formation." (PMID 25909162, 2015). "Stem cell markers Sox2, Oct4 and Nanog play pivotal roles in cancer development and drug resistance." (PMID 25686831, 2015). "Consistent with the notion that stemness and embryonic pathways can play oncogenic roles, SOX2 expression was documented in several cancers, especially of endodermal, epithelial and neural origin." (PMID 26498353, 2015). "Thecontribution of key embryonic regulators such as SOX2 points to the conservation ofcritical developmental pathways in cancer cells, which modulate their response to thedisruption of oncogenic signals." (PMID 25686219, 2015). "Of the cancer specimens, 92 of 161 cancers (57.1 %) had high expression of OCT4 (histoscore > 200) and 125 of 161 cancers (77.6 %) had high expression of SOX2 (histoscore > 30)." (PMID 26706028, 2015). "CSCs are the putative cancer-initiating cells with the characteristics of normal stem cells expressing pluripotency markers, such as Sox-2 and Oct-4." (PMID 26284927, 2015). "Stem-cell-specific transcription factors (e.g., Sox2, Klf4, Oct4, and Nanog) are frequently encountered in human cancers, and their transcriptional networks are necessary for the development and maintenance of cancer stem-like cells." (PMID 26322272, 2015).
cancer (continued). "Taken together, silencing of ANXA2 inactivate Akt pathway and repress NPC cancer stem cells through inhibiting expression of Sox2, Nanog and Oct4." (PMID 26196246, 2015). "It had been reported that many important stem cell markers such as Oct-4, Sox-2, and Nanog are highly expressed in cancer tissues and cancer cells." (PMID 26063247, 2015). "In our previous studies, SOX2 and other SOX gene family members were implicated in the development of resistance to the anti-cancer drug tamoxifen." (PMID 25997618, 2015). "SOX2 expression was reported to be correlated with tumorigenesis, chemoresistance and maintenance of stem cell-like phenotype in cancer cells." (PMID 26706028, 2015). "Although some cancer cells in the As2O3-treated xenografts remained to be SOX2 positive (GSCs), these SOX2 signal almost overlapped with the PML staining, and the majority of SOX+ cells (GSCs) were also PML-positive." (PMID 26510911, 2015). "Consistent with this notion, γ-IR was reported to induce reprogramming of cancer stem cells that express the pluripotency genes Oct4, Sox2, Nanog, and Klf4 in a Notch-dependent manner for up to 5 days post-IR." (PMID 26528440, 2015). "Many self-renewal regulatory factors, such as Oct4, Sox2, Bmi, and Nanog, are re-expressed in human malignant tumors, and they play an important role in carcinogenesis." (PMID 26063247, 2015). "Recently, SOX2 expression was documented in various cancers and suggested as a cancer stem cell (CSC) marker." (PMID 26498353, 2015). "Here, we found that silencing of ANXA2 reduced cancer stem cell formation ability and expression of CSC associated markers Oct4, Sox2 and Nanog." (PMID 26196246, 2015). "SOX2 is over-expressed in CSCs and plays an important role in tumorigenesis and recurrence of multiple human cancers." (PMID 28983346, 2015). "For some kinds of cancer cells, SOX2 has been demonstrated to hold the potential to promote cell migration and invasion." (PMID 26496354, 2015). "MiR-371-5p was necessary for SOX17 mediated cancer-related traits and SOX2 was a functional target of miR-371-5p." (PMID 25868860, 2015). "The Cancer Genome Atlas Research reported that overexpression and amplification of SOX2 were observed in 21% of SQCC samples." (PMID 25384882, 2015). "These opposing outcomes in the clinic further underscore the differing role of SOX2 in varying cancer types." (PMID 25114775, 2014). "Consistent with this, we show that the cancer stem cells, which express high levels of Sox2, lack or express very low levels of ER and, therefore, they will be more resistant to tamoxifen." (PMID 24178749, 2014). "Association with cancer was used as a third criterion in gene selection, because many early development related genes, such as NANOG, OCT4, SOX2, DPPA5A and STELLAR are relevant for cancer." (PMID 25089626, 2014). "Demethylation of the promoter of SOX2 can up-regulate its expression, which promotes proliferation and invasion of a range of cancer cells." (PMID 24889513, 2014). "Justilien and colleagues revealed the co-amplification of two oncogenes, PRKCI and SOX2, is responsible for the cancer stem cell phenotype seen in lung squamous cell carcinoma (LSCC)." (PMID 25114775, 2014). "Whole-microRNAome and genome analysis of SOX2-silenced hECCs revealed many miRNAs regulated by SOX2, including several with highly characterised functions in both cancer and embryonic stem cell (ESC) biology." (PMID 25156079, 2014). "Another key observation in this study was the heterogeneity of SOX2 expression levels within and among cancers." (PMID 25300947, 2014). "Although the precise mechanisms by which SOX2 contributes are still quite elusive, its cancer stem cell regulatory and EMT functions probably overlap." (PMID 25156079, 2014). "In recent years, Sox2 has been discovered to be aberrantly expressed in cancer cells, including those of the lungs, brain, ovaries, bone, colon, skin, and breasts." (PMID 25380620, 2014).
cancer (continued). "To date, studies have shown SOX2 to be amplified in various cancer types and affect cancer cell physiology via involvement in complicated cell signaling and protein-protein interactions." (PMID 25114775, 2014). "The mechanisms that contribute to elevated Sox2 levels in resistant cancers are not fully understood." (PMID 24178749, 2014). "Abnormal expression of SOX2 affects cell fate, proliferation, cancer progression and the control of key transcriptional processes in stem cells but little is known about its regulation." (PMID 25006803, 2014). "SOX2OT not only regulates SOX2 in vertebrate development, but also regulates SOX2 during disease processes such as cancer." (PMID 25400658, 2014). "The contradictory effect of SOX2 in cell proliferation suggests that SOX2 plays a differential role depending on the type of cancer." (PMID 25114775, 2014). "Current research has primarily focused on the direct action of SOX2 on its transcriptional target genes in the context of pluripotency, differentiation and cancer." (PMID 25156079, 2014). "In summary, SOX2 function in cancer has been accentuated in numerous cancer types in and out of the clinic and investigating SOX2’s oncogenic course is important for future prognosis, survival of cancer patients and possible therapeutic interventions." (PMID 25114775, 2014). "SOX2 has shown its potential to become a useful biomarker in the clinic for some cancer types, for both staging tumors and identification of the CSC subpopulations." (PMID 25114775, 2014). "In this review, we comprehensively compile what is known to date about SOX2’s involvement in cancer biology, focusing on the most recent findings in the fields of cellular signaling and cancer stem cells." (PMID 25114775, 2014). "Recently it has also been reported that self-renewal of cancer stem cells is maintained by SOX2, suggesting an ongogenic role of SOX2." (PMID 25010701, 2014). "Other studies have reported the amplification of the SOX2 gene in a variety of solid tumors with a possible role in cancer progression and prognosis." (PMID 25127259, 2014). "Regarding the functional importance of Sox2 in cancer, an exciting finding from our ChIP-chip study is that Sox2 was bound to the promoters of many cancer- and stem cell-associated genes in RR cells." (PMID 25380620, 2014). "Recent CSC studies have concentrated on SOX2 and its mechanisms in cancer stem cell maintenance and regulation." (PMID 25114775, 2014). "In summary, we have characterized a novel regulatory relationship between YB-1 and Sox2, two important cancer and/or stem cell transcription factors that have been implicated in the pathogenesis of BC." (PMID 24885403, 2014). "Below we highlight a few functional examples of SOX2 in cancer before we review the latest SOX2 research in different aspects of cancer physiology including: cellular proliferation, apoptosis and invasion/migration/metastasis." (PMID 25114775, 2014). "In cancers, high levels of the Sry-containing protein Sox2 are correlated with poor prognosis and increased proliferation of cancer stem cells." (PMID 25988147, 2014). "This fits with the knowledge that SOX2 is a known stem cell marker, and has been suggested to be expressed in cancer stem cells." (PMID 25010701, 2014). "Here, we consolidate SOX2’s role in cancer and provide a comprehensive overview of the field, focusing on the latest research that has implicated SOX2 in cancer biology and in the clinic." (PMID 25114775, 2014). "Although aberrant Sox2 expression is well-documented in cancer, its mechanism of action in the regulation of downstream targets is incompletely understood." (PMID 25380620, 2014).
cancer (continued). "Sox2 is strongly bound to a subset of cancer and stem cell gene promoters and can upregulate the corresponding gene transcripts in RR cells but not in RU cells." (PMID 25380620, 2014). "It has been demonstrated that Sox2 promotes key tumorigenic properties in cancer cells, including enhanced proliferation, invasion, migration, colony formation, non-adherent stem cell-associated sphere formations in vitro, and tumorigenicity in vivo." (PMID 25380620, 2014). "SOX2 has recently been directly linked to EMT and metastasis in cancer, and as an oncogene is considered to be a promoter of EMT during disease progression." (PMID 25156079, 2014). "Further, Sox2 expression has been found to correlate with a worse clinical outcome in cancer patients." (PMID 24885403, 2014). "Another critical issue that limits the potential application of iPS technology is that all four transcription factors (Sox2, Oct4, Klf4, and c-Myc) are found to be frequently overexpressed in various cancers." (PMID 25116380, 2014). "Together, these results suggest that development of tamoxifen resistance is driven by Sox2-dependent activation of Wnt signalling in cancer stem/progenitor cells." (PMID 24178749, 2014). "In recent years, Sox2 has been found to be aberrantly expressed in cancers, including those of the lungs, brain, ovaries, bone, colon, skin and breasts." (PMID 24885403, 2014). "They massively proliferated in non-adherent culture conditions and in in vivo mouse models, and the markers of cancer stem-like cells, Sox2, Oct4 and Nanog, were highly expressed." (PMID 24367661, 2013). "We believe that our results have shed important insights into the biological significance of Sox2 in BC, the invasiveness property of BC, as well as a new level of biological complexity of this type of cancer." (PMID 23815808, 2013). "Activation of the molecular targets of pluripotency-associated genes (NANOG, OCT4, SOX2, and c-MYC) is frequently observed in poorly differentiated cancers." (PMID 24023739, 2013). "ATRA reduced mammosphere-forming ability of cell lines that expressed higher levels of SOX2 suggesting that only the cancer cells that are dependent on SOX2 for self-renewal are responsive to ATRA." (PMID 23982413, 2013). "Taken together, these results demonstrated that Sox2-induced autophagy suppresses cancer growth in an in vivo xenograft mouse model." (PMID 23451179, 2013). "Isolated CD44 and CD133 cancer cells also express stem cell regulators Oct4, Sox2, nanog, and nestin." (PMID 24160469, 2013). "We examined the expression levels of CIC/CSC related markers including ALDH1, OCT4, NANOG, SOX2 and Caveolin-1 in the intralymphatic cancer cells to evaluate their relationship to lymph node metastasis." (PMID 24376714, 2013). "In univariate analyses, a low ALDH1 expression (P = 0.004) and a high SOX2 expression (P = 0.008) in cancer cells were significantly correlated with LN metastasis." (PMID 24376714, 2013). "It was also shown that ectopic expression of HIFs in cancer cell lines can induce embryonic stem cell markers, like SOX2 and NANOG." (PMID 23451260, 2013). "Recent studies demonstrate that CSC’s have higher tumorigenic properties than those of differentiated cancer cells and that the transcription factor, SOX-2, plays a vital role in maintaining the unique properties of CSC’s." (PMID 23349823, 2013). "The aberrant expression of Sox2 in cancer cells has been found to correlate with the invasiveness of several types of solid tumors." (PMID 23815808, 2013). "Re-expression of OCT4 enhanced the expression of Notch, Sox2 and Nanog molecules that play critical roles in cancer stem cell proliferation and differentiation." (PMID 23921511, 2013). "More interestingly, in several samples, we found that cancer cells with high expression of ESCs-related marker SOX2, OCT4 and Nanog, particularly SOX2, were surrounded by Nestin positive-endothelium." (PMID 23424657, 2013).